AIDA (axin interactor, dorsalization associated)
Description:
Acts as a ventralizing factor during embryogenesis. Inhibits axin-mediated JNK activation by binding axin and disrupting axin homodimerization. This in turn antagonizes a Wnt/beta-catenin-independent dorsalization pathway activated by AXIN/JNK-signaling (By similarity).
Synonyms: C1orf80; FLJ12806
Tractability: PROTAC: its protein half-life has been measured.
Gene: Protein-coding gene on chromosome 1 (222,668,013 to 222,713,210, reverse strand). Ensembl gene ENSG00000186063.
Subcellular location (Human Protein Atlas): Microtubules; Primary cilium; Basal body; Cytokinetic bridge
Gene Ontology:
Molecular function: protein binding; phosphatidylinositol binding; protein domain specific binding
Biological process: negative regulation of JUN kinase activity; determination of ventral identity; dorsal/ventral pattern formation; negative regulation of JNK cascade; negative regulation of protein-containing complex assembly
Cellular component: membrane; cytoplasm
Genetic constraint (gnomAD): Loss-of-function variants: 9 observed, 28.79 expected, observed/expected ratio (o/e) 0.31, 90% interval 0.19 to 0.55. The upper end of that interval is the gene's LOEUF score, 0.55, which puts it in group 2 of 6, group 1 being the genes least tolerant of losing a copy. Missense variants: 204 observed, 275.05 expected, observed/expected ratio (o/e) 0.74, 90% interval 0.66 to 0.83. Synonymous variants: 83 observed, 95.56 expected, observed/expected ratio (o/e) 0.87, 90% interval 0.73 to 1.04.
Homologues: Orthologues: chimpanzee AIDA (100% identical), macaque AIDA (100% identical), dog AIDA (99% identical), rat Aida (98% identical), mouse Aida (98% identical), pig AIDA (89% identical), tropical clawed frog aida (85% identical), zebrafish aida (82% identical).
Diseases named in the same sentence as AIDA in open-access papers:
AIDA is named in the same sentence as 12 diseases in open-access papers, as found by Europe PMC text mining. Sharing a sentence is not in itself a finding about the gene and the disease. The quoted sentences say what the papers report.
coronary artery disease (3 papers, 2014 to 2024). "Our study identified two proteins, PCSK9 and AIDA, linked to HF in patients with coronary heart disease (CHD), and four proteins, PCSK9, SWAP70, NCF1, and RELT, associated with HF in patients receiving antihypertensive medication." (PMID 38383373, 2024). "SNP rs2133189 was previously linked to coronary artery disease (CAD) susceptibility and is strongly linked here to peripheral artery plaque expression levels of AIDA (P < 2.1E-20)." (PMID 24973796, 2014).
atherosclerosis (2 papers, 2019 to 2025). A disease characterized by the build-up of fatty material and calcium deposition in the arterial wall resulting in partial or complete occlusion of the arterial lumen. "Our results implicate AIDA in an inflammatory response that promotes atherosclerosis and CAD." (PMID 31287004, 2019). "AIDA was the top significant protein from blood plasma, significant with both the European American and African American pQTL reference panels, a gene previously discussed as part of inflammatory response that also promotes atherosclerosis and coronary artery disease." (PMID 39670392, 2025).
diarrhoea (2 papers, 2016 to 2024). "There was a statistically significant association between the occurrence of piglet diarrhoea and the presence of the AIDA-1 (p value = 0.037) or EAST1 (p value = 0.011) gene marker among the isolates." (PMID 38802876, 2024). "For example, AIDA (adhesin involved in diffuse adherence) has been associated with E. coli strains recovered from piglets with diarrhoea, and there is evidence that it is causatively involved in diarrhoea experimentally induced in colostrum-deprived newborn piglets with STb encoding E. coli." (PMID 28405446, 2016).
endothelial dysfunction (2 papers, 2023). In vascular diseases, endothelial dysfunction is a systemic pathological state of the endothelium (the inner lining of blood vessels) and can be broadly defined as an imbalance between vasodilating and vasoconstricting substances produced by (or acting on) the endothelium. "The role of the AIDA/MIA3 locus in CAD has been discussed in terms of endothelial dysfunction through AIDA; however, MIA3 is also implicated in the modulation of vascular smooth muscle cell behaviour." (PMID 37759455, 2023). "AIDA, ARHGEF26, ADAMTS7), most are implicated in endothelial dysfunction for the first time." (PMID 36928188, 2023).
colibacillosis (1 paper, 2020). "Furthermore aidA, astA, and cnf1 might play a key role in the pathogenesis of colibacillosis, but further investigations are needed." (PMID 32344550, 2020).
nematode infection (1 paper, 2016). "B. cenocepacia trp mutants have been reported to be less virulent in a nematode infection model and the observed attenuation is possibly due to the decreased production of AidA, a quorum sensing-regulated virulence factor that has been shown to be important in the killing of C. elegans." (PMID 27597847, 2016).
pneumonia (1 paper, 2018). An acute, acute and chronic, or chronic inflammation focally or diffusely affecting the lung parenchyma, caused by an infection in one or both of the lungs (by bacteria, viruses, fungi, or mycoplasma.). "In conclusion, our findings suggest that the QS (abaR and abaI genes)/QQ (aidA gene) network plays a role in the development of bacteraemia in patients with pneumonia caused by A. baumannii." (PMID 30619184, 2018). "However, analysis of the risk factors associated with the development of bacteraemia in pneumonia caused by A. baumannii revealed underexpression of the aidA gene as the only statistically significant variable (p < 0.05)." (PMID 30619184, 2018). "We then proceeded to study the RE of the abaR and aidA genes in strains of A. baumannii from patients with pneumonia, differentiating the strains isolated from patients with bacteraemia (Pn-B) from those isolated from patients without bacteraemia (Pn-NB)." (PMID 30619184, 2018). "In this study, we analyzed the expression of Quorum network (QS/QQ) genes that differed between genomes of clinical isolates of A. baumannii, abaR and abaI (QS system) and aidA (QQ mechanism) in relation to clinical features of pneumonia and bacteraemia." (PMID 30619184, 2018). "The results did not reveal any significant differences in the RE of the Quorum network genes (abaR, aidA) between clinical strains of A. baumannii isolated from colonized patients and strains of A. baumannii isolated from patients with pneumonia (0.086/0.094 vs. 0.071/0.095, p > 0.05)." (PMID 30619184, 2018). "The Relative Expression (RE) of the abaR and aidA genes of the Quorum network (QS/QQ) was quantified by RT-qPCR analysis of the 17 isolates of A. baumannii from colonized patients and of the 13 isolates of A. baumannii from patients with pneumonia." (PMID 30619184, 2018). "Expression of the aidA gene (encoding the AidA protein, QQ enzyme) was lower (P < 0.001) in strains of A. baumannii isolated from patients with bacteraemic pneumonia than in strains isolated from patients with non-bacteraemic pneumonia." (PMID 30619184, 2018). "Moreover, we observed regulation of aidA gene expression in clinical strains of pneumonia-causing A. baumannii (non-bacteraemic pneumonia, Pn-NB) by the 3-Oxo-C12-HSL molecule (which is an AidA enzyme substrate in QQ activity) and H2O2 (an activator of the QS system)." (PMID 30619184, 2018). "The findings reveal significant differences in the expression of the abaR and aidA genes between clinical strains of A. baumannii from patients with bacteraemic pneumonia (Pn-B) and those with non-bacteraemic pneumonia (Pn-NB)." (PMID 30619184, 2018). "Results of RT-qPCR analysis of the Relative Expression (RE) of the abaR and aidA genes (Quorum network genes) in the A. baumannii isolates from patients with bacteraemic pneumonia (Pn-B) or non-bacteraemic pneumonia (Pn-NB)." (PMID 30619184, 2018). "However, in the A. baumannii strains isolated from patients with non-bacteraemic pneumonia, aidA gene expression was regulated by stressors such as 3-oxo-C12-HSL and H2O2." (PMID 30619184, 2018).
psychosis (1 paper, 2017). "For the two other antigens, DST (dystonin) and AIDA (axin interactor, dorsalization associated), seroreactivity was more prevalent in the non-psychotic controls compared to patients with first-episode psychosis." (PMID 28742074, 2017).
cancer (2 papers, 2020 to 2023). A tumor composed of atypical neoplastic, often pleomorphic cells that invade other tissues. "In addition, the combined meta-analysis identified three additional cancer risk variants (rs77753011 at RPH3A on 12q24, P = 5.5 × 10−15; rs36079339 at AIDA on 1q41, P = 3.9 × 10−10; rs2059904 at EDNRA on 4q31, P = 1.2 × 10−8), of these two were pleiotropic associations." (PMID 37340002, 2023). "AIDA, CETN3, FYB1 and POLR2D are also unfavourable prognostic markers across multiple cancer types." (PMID 32635403, 2020).
infection (2 papers, 2015 to 2022). The state of being infected such as from the introduction of a foreign agent such as serum, vaccine, antigenic substance or organism. "Although Bnr1 is immunoreactive, indicating that it is expressed during human infection, we did not detect AidA in our immunoproteomic experiments." (PMID 35212475, 2022).
tumour (1 paper, 2020). "Significantly higher transcript levels were observed in GBM tumours for AIDA (2.5-fold, p = 3.4 × 10−8), BNIP3L (1.2-fold, p = 5.5 × 10−6), CETN3 (1.8-fold, p = 1.7 × 10−7), FYB1 (1.8-fold, p = 7.25 × 10−9) and POLR2D (1.7-fold, p = 8.14 × 10−5)." (PMID 32635403, 2020). "Interestingly, AIDA, BNIP3L, CETN3, FYB1 and POLR2D were specific to GBM plasma-EV, and correspondingly, significantly higher gene expression levels were observed in GBM tumour tissue relative to healthy brain." (PMID 32635403, 2020).
AIDA also shares sentences with these, for which no sentence is quoted: prostate carcinoma (1 paper).